BTK (Bruton tyrosine kinase)
Diseases named in the same sentence as BTK in open-access papers (continued):
Sharing a sentence is not in itself a finding about the gene and the disease.
tumor (continued). "BCR engagement on CLL cells induces increased expression of these molecules and it is therefore not surprising that BTK-inhibition by ibrutinib affects tumor cells-TME cells interactions, e.g. impairing CXCR4 signaling and therefore inhibiting cellular adhesion." (PMID 34276674, 2021). "On the other hand, 3/8 (37.50%) of BTK-negative primary tumours produced BTK- positive metastases." (PMID 32912025, 2020). "Of note, most of these effects on the tumor microenvironment could not be achieved with the second generation BTK inhibitor, acalabrutinib, which is more selective to BTK and, in contrast to ibrutinib, does not target ITK." (PMID 31454887, 2019). "Furthermore, the BTK/ITK inhibitor ibrutinib efficiently limits the IL-4-producing Th2 cell population and inhibits cytokine production and direct signaling to induce the activation of tumor cells." (PMID 30814910, 2019). "Moreover, the expression of BTK-p65 is not restricted to tumor tissues only." (PMID 37685940, 2023). "However, BTK KD did not result in dramatic suppression in tumor cell presence in PB or liver." (PMID 36719376, 2023). "Therefore, the use of BTK inhibitors could result in anti-cancer activity not only in hematological malignancies, but also in solid tumors, both indirectly, via acting on the tumor microenvironment (TME), and directly, by acting on the tumor cells themselves." (PMID 31238520, 2019). "In several tumor subtypes such as lung, breast and esophageal, BTKi efficacy appears to be via other intracellular signals with a corresponding cysteine residue in the ATP binding site demonstrating that ibrutinib is not entirely specific in its binding to BTK." (PMID 29561760, 2018). "Also in BTK-negative solid tumors that do not express BTK, its inhibition may hold promise as multiple cell types in the tumor microenvironment are regulated by BTK." (PMID 29455639, 2018). "As expected, the TIMER database showed a significant positive correlation between BTK and DPEP2 expression and immune cell infiltration and a significant negative correlation with tumor purity." (PMID 36991102, 2023). "In contrast, the BTK-p80 isoform was not detectable in Moe1a, Moe1b and TIGK cells, which represent non-tumor cell lines derived from oral epithelium." (PMID 36612306, 2023). "A dominant kinase activity derived from the tumour tissue, but not patient-derived GBM stem-like cell lines, was Bruton tyrosine kinase (BTK)." (PMID 34645618, 2021). "The synchronously change of CYLD phosphorylation and BTK phosphorylation suggested that CYLD phosphorylation should be regulated through inhibition of BTK phosphorylation, which might regulate tumor cell death in non-GCB-DLBCL." (PMID 33827598, 2021). "However, BTK inhibition using ibrutinib had no impact on IRF4 level in WM, nor did it increase WM tumor cells sensitivity to lenalidomide and pomalidomide." (PMID 29348877, 2017). "MALT1 KO, but not CARD11 KO, was able to dramatically diminish the tumor growth and dissemination in vitro and in vivo in the resistant MCL cells, supporting our notion that MALT1 hyperactivity critically contributes to IBN resistance via bypassing BTK/CARD11 upstream signaling." (PMID 36719376, 2023). "Importantly, our data also indicate that the combination of CER-1236 with either a BTK or EGFR inhibitor did not result in toxicity to normal tissues, nor does it affect peripheral blood counts or clotting kinetics, indicating the selectivity of the anti-tumor immune response." (PMID 37194236, 2023).
cancer (225 papers, 2009 to 2026). A tumor composed of atypical neoplastic, often pleomorphic cells that invade other tissues. "Solid tumors as breast cancer, pancreatic cancer and other types of cancer are directly or indirectly mediated by aberrant BTK expression or mutations." (PMID 39925800, 2025). "Studies have shown that elevated expression of genes associated with cancer aggressiveness and stemness is linked to high Bruton’s tyrosine kinase (BTK) expression in solid tumors." (PMID 41145013, 2025). "While our review shows the use of BTK inhibitors in the management of autoimmune bullous diseases associated with advanced lymphoproliferative malignancies, such as CLL, this case demonstrates its efficacy in the management of early lymphoproliferation." (PMID 39507482, 2024). "Alisertib, an AK-A inhibitor that causes cancer cell arrest in the G2/M phase, would conceivably be in tandem with a BTK inhibitor that targets cell growth to restore the response to BTK inhibitors." (PMID 39766156, 2024). "Since BTK is implicated in cancers, there are numerous investigations of inhibitors and drug resistance." (PMID 40225173, 2023). "These mutations caused prolonged and BTK-independent activation of NF-κB, resulting in cancer cell proliferation and migration." (PMID 36183125, 2022). "On the whole, data reported so far about the role of BTK in solid tumors suggest that its increased expression is associated to worse prognosis, to advanced cancer metastatic potential, drug-resistance and stemness." (PMID 34164404, 2021). "Recent examples of kinase inhibitors targeting cancer-associated immune cells include small molecule inhibitors directed towards Bruton’s tyrosine kinase (BTK), colony-stimulating factor-1 receptor (CSF-1R), and PI3Kgamma." (PMID 31817861, 2019). "Pharmacological BTK inhibitors in vivo affected S. aureus clearance in mice and IL-1β release in cancer patients, which was associated with a reduced ability of isolated PBMC to secrete IL-1β." (PMID 29167667, 2017). "However, there is considerable heterogeneity across patients concerning the cancer cell fraction bearing BTK mutations." (PMID 41213958, 2025). "Potential targeting of the scaffold functions of BTK, could disrupt crucial protein–protein interactions, vital for the survival of the cancer cells and reverse the resistance driven by mutations in the kinase domain of BTK." (PMID 39456530, 2024). "Variations in CYP3A genotype have been associated with altered metabolism for several non-cancer drugs and could alter BTK inhibitor metabolism." (PMID 37185435, 2023). "In addition, six tumor suppressor genes previously implicated in cancer (BTK, CHD1, FN1, NFATC2, NOTCH1, and NRP1) were found in at least two samples." (PMID 34489456, 2021). "Overexpression of BTK in solid tumor cells was associated with elevated expression of genes with functions related to cell adhesion, cytoskeletal structure, and extracellular matrix as well as aggressiveness of the cancer." (PMID 33937249, 2021). "It has been found that cancer patients treated with BTK inhibitors may acquire resistance by BTK mutations at cysteine 481, which is required for covalent binding and poses a problem for covalent BTK inhibitors in these subpopulations." (PMID 34803999, 2021). "Inflammation is an underlying cause of several cancers, and BTK might modulate cancer progression in this way." (PMID 34307353, 2021). "Originally discovered in patients with immunodeficiency X-linked gammaglobulinemia, the Bruton’s tyrosine kinase (BTK) signaling pathway, known for its role in B cell maturation, is critical to cancer cell proliferation, metastasis and evasion of cancer eliminating cells." (PMID 34063667, 2021). "Similarly, aberrations in signaling cascades linked with BTK enhance uncontrolled B-cell proliferation, and further investigation along these lines on BTK will thus be useful for the development of novel targeted cancer therapies." (PMID 41266486, 2025).
cancer (continued). "Furthermore, the overexpression of this BTK isoform on cancer cells has been associated with an increased expression of the genes with functions related to cell adhesion, cytoskeletal structure and extracellular matrix, as well as higher aggressiveness of cancer and a worse clinical outcome." (PMID 35456016, 2022). "Although the expression of BTK may be affected by the number of immune cells, it is considered that after chemotherapy and radiotherapy will cause the decline of immune cells, we speculate that BTK here may be highly expressed by CCRT-resistance OSCC cancer cells." (PMID 33640903, 2021). "Our data suggest that DAPK3 inhibition could be an alternative to ibrutinib treatment in CLL, particularly in cases where resistance is associated with BTK/ PLCγ2 mutations, but also more generally in cancers characterised by DAPK1‐silencing, which is a common marker of poor prognosis." (PMID 32306542, 2020). "The introduction of these small BTK inhibitors changed the paradigm of cancer therapy for various leukemias." (PMID 41266486, 2025). "Recently, BTK inhibitors such as ibrutinib have significant advancement in B-cell malignancies and cancers." (PMID 39744694, 2025). "A more recent report on CLL patients with dual resistance to BTK inhibition and Bcl-2 antagonism has identified emerging BCL2 mutations in 4 out of 11 cases, with only 2 characterized by a mutated cancer cell fraction above 25%." (PMID 41213958, 2025). "Early clinical trials targeting the androgen receptor, estrogen receptor, and BTK (Bruton tyrosine kinase) have demonstrated encouraging efficacy and safety profiles, highlighting the potential of protein degraders as a new class of cancer therapeutics." (PMID 40558489, 2025). "For example, notable cysteine-reactive covalent drugs such as ibrutinib and acalabrutinib have transformed cancer therapy by selectively inhibiting Bruton’s tyrosine kinase (BTK) through a covalent mechanism, with minimal off-target effects on other kinases." (PMID 40894761, 2025). "Further analysis of NGS identified two novel missense mutations, D326E in BTK (Bruton’s tyrosine kinase) at SH2 domain and D251E in EPHA5 (EPH receptor A5), along with other known cancer- associated mutations." (PMID 39925800, 2025). "For example, the profile of the Bruton’s tyrosine kinase (BTK) inhibitor ibrutinib in the Oncolines® cancer cell line panel shows similarity with that of epidermal growth factor receptor (EGFR) tyrosine kinase inhibitors." (PMID 41199836, 2025). "The B-cell receptor pathway is actively involved in the proliferation and survival of cancer cells, and Bruton tyrosine kinase (BTK) is an important component of this signaling pathway." (PMID 39050755, 2024). "In recent years, BTK inhibitors have attracted considerable attention as potential therapeutic agents for a range of diseases, including B-cell malignancies and autoimmune disorders." (PMID 39063112, 2024). "The BCR pathway is essential for the proliferation and survival of cancer cells in various B-cell malignancies, with BTK being a key component." (PMID 39777345, 2024). "Collectively, these results have provided information on the safety and efficacy of this combination in patients with cancer, while the present study provides detailed information on the short-term effects of BTK inhibition." (PMID 39513363, 2024). "By understanding how BTK inhibitors can impact cancer cells and the immune system, this paper highlights the potential for these drugs to be used in a wider range of medical conditions." (PMID 39518015, 2024). "JNJ-64264681 is a covalent, irreversible BTK inhibitor that has shown good oral efficacy in both cancer and autoimmune models and has entered human clinical studies." (PMID 39777345, 2024).
cancer (continued). "MRS is emerging as particularly effective in detecting and monitoring biomarkers of response to kinase inhibition, as shown using MCL as cancer model and the Bruton’s tyrosine kinase (BTK) inhibitor ibrutinib, as index kinase inhibitor." (PMID 39161974, 2024). "Bruton’s tyrosine kinase (BTK) is pivotal in B-cell signaling and a target for potential anti-cancer and immunological disorder therapies." (PMID 39063112, 2024). "Regarding CLL, BTK has a role in the milieu surrounding the cell, where it plays a role in assisting cancer cells in their development and survival." (PMID 38671922, 2024). "Though they are FDA-approved for B cell malignancies, unacceptable toxicities of the first- and second-generation BTK inhibitors (BTKis) have limited their application to non-cancer indications." (PMID 38492772, 2024). "In the decade since Ibrutinib received FDA approval, it and other BTK inhibitors are now broadly used in cancer treatment providing patients with excellent strategies to manage B cell malignancies." (PMID 37651403, 2023). "Ibrutinib was the pioneering BTK inhibitor to receive approval, significantly altering the standard‐of‐care treatment for various cancers, including mantle cell lymphoma, marginal zone lymphoma, and several others." (PMID 37929016, 2023). "Although BTK inhibitors are now generally given as monotherapy, combination therapies with other anti-cancer agents are being evaluated in clinical trials with great promise as well as next generation reversible BTK inhibitors." (PMID 37185435, 2023). "Ibrutinib is the first FDA approved BTK inhibitor for cancer therapy and often used as a positive control when designing new BTK inhibitors." (PMID 37628906, 2023). "Like other anti-cancer drugs, adverse effects and resistance to the covalent BTK inhibitors were observed." (PMID 36986499, 2023). "In recent years, some researchers have shown that targeting the BTK signal in the solid tumor microenvironment is feasible for cancer treatment." (PMID 37638060, 2023). "BTK plays a crucial role in immune system function and cancer development, making it an attractive target for therapeutic intervention." (PMID 37848584, 2023). "The effect of the tested BTK inhibitors on ERBB signalling was analysed in cancer cell lines stimulated by heregulin; a similar experimental setup was used in a recently published study with ibrutinib." (PMID 36913160, 2023). "BTK is crucial for several active pathways involved in cancer cell survival, including protein kinase B (AKT) and p44/42 MAPK." (PMID 37929016, 2023). "Bruton's tyrosine kinase (BTK) is a protein kinase that plays a crucial role in various biological processes, including immune system function and cancer development." (PMID 37848584, 2023). "Bruton’s tyrosine kinase (BTK) inhibitors are currently under exploration for diverse cancers and neurological disorders, and they have been a target of large interest for PET radioligand development (vide supra)." (PMID 37513867, 2023). "In this review article, we summarize the most recent findings regarding this kinase as well as the most advanced BTK inhibitors that have been developed to date and their clinical applications mainly in cancer and chronic inflammatory disease patients." (PMID 36903645, 2023). "We tested the BTK inhibitor Ibrutinib and AgNPs combination, since Ibrutinib sensitizes cancer cells to ROS inductor agents." (PMID 37509279, 2023). "Herein, we used the same incubation time (1 h) and drug concentrations previously used in BTK inhibition studies in cancer cells, and reflected the exposure of platelets to the pharmacologically active fractions of the drugs in vivo." (PMID 36497231, 2022). "Despite having a large sample size of patients with cancer, we were limited in our sample of patients who received certain targeted therapies (eg, BTK inhibitors, venetoclax, CD19-CAR-T, and B-cell maturation antigen CAR-T)." (PMID 35266953, 2022).
cancer (continued). "The constitutive activation of MYD88 activates the downstream pathway, such as Bruton’s tyrosine kinase (BTK) and NF-kB proteins, which favor cancer cell survival and proliferation." (PMID 35349079, 2022). "Understanding the role of BTK in the B-cell signaling pathway has led to the development of BTK inhibitors (BTKi) as effective therapies for malignancies of myeloid origin and exploration as a promising therapeutic option for other cancers." (PMID 36294458, 2022). "In the in vitro evaluation, the inhibition of this isoform decreased the growth and survival of cancer cells, thus serving as a rationale behind the potential feasibility of BTK inhibitors in this type of cancer." (PMID 35456016, 2022). "π-stacking, H–π interactions, and increased selectivity, which translates into lower toxicity, are functions of the phenoxy moiety for agents with anti-cancer activity and BTK inhibitors." (PMID 36012142, 2022). "We have demonstrated that dual and triple action TP-scaffold compounds show promising results as anti-cancer agents, and the first generation of BTK/PI3K/BRD4 inhibitors, such as SRX3262, was cytotoxic to MCL cells." (PMID 35031886, 2022). "In this perspective we briefly summarize the progress made in the last decade in studying BTK and its isoforms in cancer cells and define the open questions to be addressed in order to get the most benefits from its targeting for therapeutic purposes." (PMID 35992808, 2022). "Although this meticulous network comprises numerous pathways, the BTK signaling pathway is among the most vital ones for cancer progression." (PMID 35456016, 2022). "As discovered, the inhibition of this BTK isoform inhibited cancer cell growth and apoptosis and enhanced chemosensitivity, thus making targeting it an attractive opportunity for anti-cancer therapies." (PMID 35456016, 2022). "Over the past decade, new targeted therapeutic approaches such as bruton’s tyrosine kinase (BTK) inhibitors and Bcl2 blockers as well as innovative therapies that modulate the immune response against cancer cells." (PMID 36064322, 2022). "Based on studies in cancer cells, these concentrations (≤20 nM) are sufficient to inhibit BTK in vitro (and in vivo)." (PMID 36497231, 2022). "The promise of targeting ITK in cancer is bolstered by the growing success of targeting protein family member BTK, which plays a similar role in B cells and B cell tumors." (PMID 35911672, 2022). "Clinical studies on another PTK, Bruton tyrosine kinase (BTK) inhibition revealed the ameliorating cancer in SARS-CoV-2 patients." (PMID 35356629, 2021). "Another possible consequence of BTK signaling in cancer cells is the recently discovered involvement of BTK in activating the inflammasome through ASC phosphorylation." (PMID 34307353, 2021). "The compound reduced the activity of BTK enzyme with high selectivity and effectively suppressed the proliferation of cancer cell in vitro." (PMID 34277564, 2021). "Numerous clinical trials of BTK inhibitors in cancers were initiated in the last decade, and ~73 trials were intensively announced or updated with extended follow-up data in the most recent 3 years." (PMID 33122850, 2021). "PI3K-dependent BTK signaling is a key example of a PI3K network that has emerged as an effective therapeutic target in cancer." (PMID 34356110, 2021). "Ibrutinib is an orally administered tyrosine kinase inhibitor (TKI) targeting Bruton's tyrosine kinase (BTK) that has transformed the treatment for cancers driven by B-cell proliferation." (PMID 34950932, 2021). "BTK isoforms expressed in diverse cancer types are critical signaling effectors that respond to the increased production of PIP3 that is common to these cells." (PMID 34307353, 2021). "Recent evidence regarding novel splice variants of BTK in colon and breast cancer expand its significance from the well-known and critical role of BTK in malignant B cells." (PMID 33718366, 2021).